CXCR3 (C-X-C motif chemokine receptor 3)
Diseases named in the same sentence as CXCR3 in open-access papers (continued):
Sharing a sentence is not in itself a finding about the gene and the disease.
infection (continued). "Furthermore, both induction of the CXCR3 chemokine interferon-gamma-inducible protein-10 (IP-10) and expression of MMP-9 in human lung tissue following ex vivo infection with Chlamydia pneumoniae were previously demonstrated by in situ hybridization in human lung specimens." (PMID 17567922, 2007). "Therefore, levels of CXCR3 (receptor for CXCL9 and CXCL10), CXCR5 (receptor for CXCL13), CCR5 (receptor for CCL3 and CCL5), and CCR7 (receptor for CCL19) were analyzed on CD45hiCD11bloCD19+ B cells which infiltrated the brain at 7, 14, 30, and 60 days post infection." (PMID 27207308, 2016). "Interestingly, the majority of brain-sequestered T cells found in anti-IP-10-treated mice expressed CXCR3, suggesting that in the absence of IP-10 other CXCR3 ligands are able to mediate trafficking to the brain during infection but at levels that are not sufficient to induce severe disease." (PMID 19343215, 2009). "The salivary gland constitutively recruits CD8+ T cells in a CXCR3-dependent manner and is capable of inducing and sustaining TRM populations even in the absence of infection, antigen, or inflammation." (PMID 41479900, 2025). "In their compelling paper, mice lacking CXCR3 or CXCL10 and subjected to IFN-β treatment or infection with the virus were protected from depressive-like behaviour." (PMID 38414751, 2024). "We did not investigate if any specific chemokine receptors (e.g., CXCR3, CCR5, or CX3CXR1) impact the success rate of the T cell search for the infection site." (PMID 36303744, 2021). "In both the blood and brain, CXCR3 expression on CD8+ and CD4+ T cells was up-regulated upon infection, but no detectable difference was found between WT and Pbyop1Δ parasite-infected mice." (PMID 34025654, 2021). "Clinically affected cows demonstrated significantly higher numbers of CXCR3+ (Th1-type) and CCR9+ (total small intestinal lymphocytes) cells at the site of infection compared to the subclinical cows and noninfected controls." (PMID 33849661, 2021). "Our study is descriptive, and the key claim that the abrogated CXCR3/CXCL10 axis is DPP4-mediated and occurring at the site of infection remains circumstantial without direct confirmation." (PMID 30026741, 2018). "Primary, but not secondary, Ad5hr inoculation increased the frequency of CXCR3+ CD4+ T cells in blood, while secondary, but not primary, Ad5hr infection transiently increased the frequencies of Ki67+, HLADR+ and CD95+/CCR5+ CD4+ T cells in blood." (PMID 25203111, 2014). "The expression of CXCR3 did not change in CD16+ and DN cells during MPXV infection, but slightly decreased in CD56+ and DP cells (p>0.05)." (PMID 24147080, 2013). "Similarly, over 70% of αβT cells recovered from brains of anti-IP-10-treated mice expressed this receptor, suggesting that 8A7 blocking effect of IP-10 may not be absolute or that in the absence of IP-10 other CXCR3 chemokines can recruit leukocytes to the brain during infection." (PMID 19343215, 2009). "Comparison of the frequencies of CXCR3+ cells as a fraction of non-naïve (CD95+) CD8+ and CD4+ T cells over time provided further evidence of more efficient homing of T cells to the site of infection in the younger animals." (PMID 35039442, 2022). "In summary, the findings of the current study indicate that clinically infected cows have higher numbers of CXCR3+ (Th1-type) and CCR9+ (total small intestinal T cells) cells at the site of infection when compared to subclinically infected and noninfected control cows." (PMID 33849661, 2021). "We found that the majority of CD11b+ LyChi Ly6G- CD64+ inflammatory monocytes present in the ear of VACV-infected mice at 5 days post-infection were CCR5+, the receptor for CCL4, rather than CCR2+, or positive for the receptors for CXCL13 (CXCR5) or CXCL9 and CXCL10 (CXCR3)." (PMID 31603920, 2019). "Prior to infection, mice did not have a distinct population of CD127+CXCR3+ CD8 T cells." (PMID 29963060, 2018).
infection (continued). "However, Cxcr3−/− mice receiving Cd40l−/− CD4+ T cells survived the infection, indicating that CD40L does not mediate CXCR3+CD4+-dependent protection." (PMID 24130498, 2013). "While we showed that CXCR3+ Tfh and B cells are activated in AHI and could play an important role in HIV-specific antibody development, it is not clear whether a similar role of CXCR3+ Tfh and B cells would occur in infections that do not induce a strong Th1 response." (PMID 39932316, 2025).
cancer (289 papers, 2004 to 2026). A tumor composed of atypical neoplastic, often pleomorphic cells that invade other tissues. "Ligand-based target prediction combined with k-means clustering suggested CXCR3, a chemokine receptor implicated in cancer drug resistance, as a plausible target for the in-house collection." (PMID 42255641, 2026). "We validated that high CD8A and CXCR3 levels were associated with a better survival rate in all cancer patients treated with immunotherapies." (PMID 38953994, 2024). "These receptors, such as ACKR3, CXCR4, CXCR3, play a crucial role in the regulation of the immune system, are associated with inflammatory diseases and cancer, and are seen as promising drug targets." (PMID 38732237, 2024). "Cxcr3 is expressed on a subset of Foxp3 + regulatory T cells (Treg) and Cxcl10 expression by cancer-associated fibroblasts can recruit suppressive Treg." (PMID 36472588, 2023). "Cxcr3 and its ligands are associated with a T cell inflamed signature in many cancers and plasma levels of Cxcl9 and Cxcl10 are associated with prolonged survival in PDA patients treated with chemotherapy." (PMID 36472588, 2023). "Other SASP chemokines such as CXCL9/10 that bind to CXCR3 and are associated with T cell recruitment and “hot” TMEs in other cancer settings are necessary for CD8+ T cell recruitment into PDAC following therapy-induced senescence." (PMID 37142692, 2023). "In humans, three splice variants of CXCR3 (CXCR3A, CXCR3B, and CXCR3-alt) have been discovered, and these variants play distinct roles in different types of cancer cells." (PMID 37664052, 2023). "While the CXCL9/10/11/CXCR3 axis is more generally associated with antitumorigenesis, studies of its participation in cancer growth and metastasis have been published." (PMID 36164329, 2022). "The receptor for CXCL10, CXCR3, has a pleiotropic role across cancer models and has been variously associated with recruitment of effector and suppressive/regulatory T cell populations." (PMID 35844527, 2022). "The most studied receptor of CXCL10 is CXCR3 (LR pair associated with immune response in 12 of the 18 cancer types), which is expressed by effector CD8+ T cells, T helper 1 cells, and NK cells, which are all antitumor lymphocytes." (PMID 34430923, 2021). "In cancer, IP-10 can either inhibit or promote tumors depending on the corresponding spliced variant of the its receptor CXCR3." (PMID 34214127, 2021). "Expression of seven CXCR members was closely associated with cancer stages of ccRCC patients, and patients with late stages (stage 3–4) tended to have higher mRNA expression of CXCR3/5/6." (PMID 33324682, 2020). "Defects in CXCR3 signaling have also been associated with other immune-related diseases, including cancer and inflammatory disorders." (PMID 25573892, 2015). "Recent research has indicated that CXCR3/chemokines interactions that orchestrate haematopoetic cell movement are implicated in the metastatic process of malignant tumours, including that of CRC cells to lymph nodes." (PMID 19436305, 2009). "To validate our model, we tested the individual PaC cell and the combined effects with cancer-associated fibroblasts (CAFs) on cancer tumorigenicity, the cellular interaction through the CXCR3/CXCL10 axis, and cellular responses reflection of anti-cancer treatments." (PMID 38495500, 2024). "Similarly, while the binding of CXCL10 to the chemokine receptor CXCR3-B inhibits cancer cell proliferation, it can also activate another splice variant of CXCR3, CXCR3-A, which can induce chemotaxis and cancer cell proliferation." (PMID 38543085, 2024). "Similarly, high CXCR3 expression was associated with better survival in some cancers and worse prognosis in others." (PMID 34440489, 2021). "Herein, we found the CXCR3 isoform dominance shifts during cancer associated phenotypic shifts." (PMID 31831069, 2019). "CXCR3 has been detected in many malignant tumors and is associated with patient outcomes." (PMID 31737787, 2019).
cancer (continued). "Although CXCR3 expression by tumor cells is associated with worse prognosis in these cancers and CXCR3 ligands may also attract tumor-promoting regulatory T cells, the net effect of CXCR3 chemokine overexpression seems to favor tumor suppression." (PMID 31482487, 2019). "Using CXCL10 as a representative of CTL-attracting chemokines, involved in attraction of CXCR3+ CTL implicated with good prognosis for cancer patients, we tested whether BCG treatment can enhance intra-tumoral production CXCL10." (PMID 25806105, 2015). "Mph), which promotes CD4+ T cell accumulation via CXCL10/CXCR3 for HLA-DR+ Schwann cells and assists them in shaping the cancer-neuron-immune niche and facilitating HNSCC progression." (PMID 42295734, 2026). "We studied three isoforms of CXCR3, which have mostly been studied in various cancers, with CXCR3A identified as a chemokine receptor, with its functional activities being modulated by the CXCR3B and CXCR3alt variants by the formation of various heterodimers." (PMID 41273416, 2026). "Along with our pilot study, studies showed that an inhibition of this loop has an inhibitory effect on cancer cell growth, and the CXCR3 axis is proposed to be a target for treatment." (PMID 40362215, 2025). "Fibroblast-derived CXCL9/10 also promotes lung metastasis by stimulating the growth of CXCR3+ cancer cells." (PMID 40447617, 2025). "In this study, we have demonstrated that CXCR3 would localize to the mitochondrial membrane and exert a previously unrecognized function in regulating cancer metabolism and mitochondrial function." (PMID 40185710, 2025). "While CXCR3-alt’s function remains poorly understood, CXCR3-A and CXCR3-B exhibit opposing effects that often govern cellular fate in cancer." (PMID 41516196, 2025). "We suggest further exploration of the CXCR3 axis, its ligands, and exercise in multiple cancer models, as there is a strong link between this pathway and the direct effect of exercise on cancer cells." (PMID 40362215, 2025). "Previous studies have shown that IRI triggers cancer recurrence through CXCL10/CXCR3 signaling to mobilize regulatory T cells." (PMID 40524699, 2025). "When CXCL10 binds to its receptor CXCR3 on ‎cancer cells or immune cells, it can activate the MAPK/ERK signaling pathway, leading to various ‎cancer-related processes." (PMID 40760734, 2025). "Our findings reveal CXCR3 as a previously unrecognized regulator of mitochondrial function in cancer cells, positioning the CXCR3-mitochondrial signaling axis as a promising therapeutic target for GBM." (PMID 40185710, 2025). "Taken together, these results suggest that miR-762 attenuates T-cell cytotoxicity against cancer by reducing the expression levels of CXCR3." (PMID 39940842, 2025). "In OSCC, CXCR3 enhances lymphatic invasion and cancer growth, while CXCR3A promotes cancer stemness and chemoresistance, indicating CXCR3 is important for OSCC progression." (PMID 39940842, 2025). "The heatmap displayed that GPX4 expression was highly correlated with the levels of numerous chemokines and chemokine receptors, such as CXCL16, CCL28, CX3CL1, CCL5, CCR10, CXCR5, and CXCR3, across the majority of cancer types." (PMID 41142608, 2025). "This review provides an overview of the structure and signaling pathways of CXCR3, its biological functions in cancer and inflammatory diseases, and highlights the innovative roles of CXCR3 in these diseases." (PMID 40786052, 2025). "The diverse functions of CXCR3 underscore its potential as a target for immunotherapy and its significance in cancer and immune regulation." (PMID 39940842, 2025). "CXCL9, CXCL10, and CXCL11 are selective ligands for the C‐X‐C motif chemokine receptor 3 (CXCR3) and are secreted by cancer cells." (PMID 40105652, 2025). "CXCR3+ macrophages, in particular, play a key role in immune activation and have been identified as promising targets in cancer." (PMID 40858590, 2025).
cancer (continued). "Certain receptors display consistent co-regulation patterns across cancer tissues and subtypes even if bound to multiple ligands (e.g., CXCR3, CCR3, CCR5)." (PMID 38723607, 2024). "We have reported CXCR3 to be concordantly upregulated together with its ligands across cancer subtypes." (PMID 38723607, 2024). "Studies have revealed that CXCR3+ CD4+ T cells were critical in preventing persistent HPV infection and cancer progression, while CXCR3+ CD4+ Trm cells were irreversibly depleted in patients with advanced HIV disease." (PMID 39902182, 2024). "CXCR3 is highly expressed in metastatic cancer cells, and its binding with chemokine ligands, such as CXCL10, enhances the migration and invasive motility of cells." (PMID 38275412, 2024). "Based on these findings, we examined CXCR3/CXCL11-axis-mediated chemotactic activity in cancer and CD8+ T cells." (PMID 39543650, 2024). "By analyzing the immune landscape of NBL, we identified six genes - BATF, CXCR3, GIMAP5, GPR8, IGHM, and ISG20-with diagnostic and clinical significance in other cancers, but whose roles in NBL remain largely unexplored." (PMID 39559348, 2024). "Collectively these accumulating data indicate, not only a pivotal role of the CXCR3 axis in anti-cancer immunity, but also that one of the major mechanisms by which the immune ICB function is via the CXCR3 axis." (PMID 39474427, 2024). "CXCL10 and its corresponding receptor CXCR3 are highly expressed by various cell types, including leukocytes and macrophages as well as some epithelial and cancer cells in a wide range of human disorders." (PMID 39268223, 2024). "The chemokine receptor CXCR3 is predominantly expressed on the surface of macrophages, T cells, NK cells, dendritic cells, and cancer cells." (PMID 39596815, 2024). "In preclinical cancer models, CXCR3 chemokine activity was shown to be crucial for effective immune checkpoint inhibition, owing to CXCR3's role in both T-cell recruitment and T-cell activation." (PMID 38590525, 2024). "Consistent with the findings of a previous study, we observed that the binding of CXCL11 to CXCR3 on CD8+ T cells enhanced the apoptotic rate of cancer cells." (PMID 39543650, 2024). "Conversely, inhibition of CXCR3 suppresses the migration of cancer cells and expressions of EMT-related molecules." (PMID 39543650, 2024). "They boost the host immunity during NSCLC immunotherapy by increasing Th1 lymphocytes and in IL‐12‐dependent manner, boosting the amount of IFN‐γ, and attracting CCR9 + CXCR3 + CD4 + T cells towards cancer cells." (PMID 38571678, 2024). "As expected, CXCR3 levels also distinguished patients' survival outcomes, and the levels of CXCR3 differed significantly in cancer and adjacent normal tissues." (PMID 37692506, 2024). "Apart from driving infiltration of NK cells into solid tumors, CXCR3 is also preferentially expressed on a number of cancer cells." (PMID 38264648, 2023). "CXCL9-10-11 are selective ligands for CXCR3, which is preferentially expressed on the surface of monocytes, T cells, NK-cells, dendritic cells and cancer cells." (PMID 38107068, 2023). "IFN-γ promotes migration of immune cells to TME by transcriptionally regulating the expression and secretion of CXCL9, CXCL10 and CXCL11 and their cognate receptor CXCR3 in T cells, NK cells, monocytes, DCs and cancer cells." (PMID 37646041, 2023). "CXCR3 is a receptor that is preferentially expressed on the surfaces of monocytes, T cells, NK cells, dendritic cells, and cancer cells." (PMID 37493737, 2023). "Previous studies reported the high expression of CXCR3, and PD-L1/PD-1 was related to cancer invasion." (PMID 36726488, 2023). "Ultimately, however, Cxcr3 was critical for mitigating cancer cell dissemination following immunotherapy with CD40 agonist + anti-PD-L1 or T cell receptor engineered T cell therapy targeting mesothelin." (PMID 36472588, 2023). "As CXCR3 has been studied for years, its effect on cancer is more well-known and convenient for clinical applications." (PMID 36750966, 2023).